CPT2 (carnitine palmitoyltransferase 2)
Description:
Involved in the intramitochondrial synthesis of acylcarnitines from accumulated acyl-CoA metabolites. Reconverts acylcarnitines back into the respective acyl-CoA esters that can then undergo beta-oxidation, an essential step for the mitochondrial uptake of long-chain fatty acids and their subsequent beta-oxidation in the mitochondrion. Active with medium (C8-C12) and long-chain (C14-C18) acyl-CoA esters.
Synonyms: CPT1; CPTASE; IIAE4
Tractability: Small molecule: an approved drug acts on it; a high-quality ligand is known; it belongs to a druggable protein family. Antibody: UniProt places it where antibodies can reach, with medium confidence. PROTAC: ubiquitination databases record sites on it; its protein half-life has been measured; a small molecule that binds it is known.
Target class: Enzyme; Transferase
Gene: Protein-coding gene on chromosome 1 (53,196,792 to 53,214,197, forward strand). Ensembl gene ENSG00000157184.
Subcellular location: Mitochondrion inner membrane
Subcellular location (Human Protein Atlas): Mitochondria; Nucleoplasm; Nucleoli
Pathways (Reactome):
Metabolism: Carnitine shuttle; PPARA activates gene expression
Gene Ontology:
Molecular function: acyltransferase activity; carnitine O-acyltransferase activity; carnitine O-octanoyltransferase activity; carnitine O-palmitoyltransferase activity; protein binding
Biological process: carnitine metabolic process; fatty acid beta-oxidation; long-chain fatty acid metabolic process; carnitine shuttle; positive regulation of cold-induced thermogenesis; long-chain fatty acid transport
Cellular component: mitochondrion; mitochondrial inner membrane; mitochondrial matrix
Genetic constraint (gnomAD): Loss-of-function variants: 33 observed, 42.53 expected, observed/expected ratio (o/e) 0.78, 90% interval 0.59 to 1.04. The upper end of that interval is the gene's LOEUF score, 1.04, which puts it in group 4 of 6, group 1 being the genes least tolerant of losing a copy. Missense variants: 764 observed, 823.34 expected, observed/expected ratio (o/e) 0.93, 90% interval 0.87 to 0.99. Synonymous variants: 314 observed, 320.26 expected, observed/expected ratio (o/e) 0.98, 90% interval 0.89 to 1.08.
Gene-disease validity (ClinGen):
ClinGen rates the evidence that CPT2 causes each of these diseases.
carnitine palmitoyltransferase II deficiency (autosomal recessive): Definitive. Carnitine palmitoyltransferase II (CPT II) deficiency is an inherited metabolic disorder that affects mitochondrial oxidation of long chain fatty acids (LCFA).
Homologues: Orthologues: chimpanzee CPT2 (99% identical), macaque CPT2 (98% identical), guinea pig CPT2 (89% identical), mouse Cpt2 (87% identical), pig CPT2 (85% identical), rat Cpt2 (83% identical), rabbit CPT2 (83% identical), dog CPT2 (83% identical), tropical clawed frog cpt2 (71% identical), zebrafish cpt2 (69% identical), Drosophila melanogaster CPT2 (45% identical), Caenorhabditis elegans cpt-2 (44% identical). Paralogues in human: CRAT (29% identical), CPT1B (28% identical), CPT1A (28% identical), CPT1C (28% identical), CROT (27% identical), CHAT (27% identical).
Diseases named in the same sentence as CPT2 in open-access papers:
CPT2 is named in the same sentence as 206 diseases in open-access papers, as found by Europe PMC text mining. Sharing a sentence is not in itself a finding about the gene and the disease. The quoted sentences say what the papers report.
rhabdomyolysis (19 papers, 2012 to 2025). Necrosis or disintegration of skeletal muscle often followed by myoglobinuria. "We discussed a clinical case of myopathic CPT2 deficiency diagnosed in a middle-aged adult who presented with rhabdomyolysis following an influenza illness." (PMID 39850164, 2024). "We present a case of a patient who had recurrent episodes of rhabdomyolysis and was found to have CPT2 deficiency." (PMID 39850164, 2024). "Carnitine palmitoyltransferase 2 (CPT2) is the most common disorder of fatty acid oxidation and has documented association with recurrent rhabdomyolysis, especially with certain triggers like fever, infection, statins, and exposure to temperature extremes." (PMID 39497864, 2024). "It is typically associated with recurrent episodes of exercise-induced rhabdomyolysis and myoglobinuria, in most cases caused by a c.338C > T mutation in the CPT2 gene." (PMID 31191612, 2019). "A clinical trial reported improved exercise tolerance and reduction of rhabdomyolysis episodes under bezafibrate treatment in all six CPT2-deficient patients tested." (PMID 29926323, 2018). "We report the efficacy of fenofibrate in a patient with CPT2 deficiency, in whom beta-oxidation was improved but an episode of rhabdomyolysis nevertheless occurred." (PMID 23326270, 2012). "Bezafibrate therapy has been shown to improve beta-oxidation of fatty acids and to reduce episodes of rhabdomyolysis in patients with carnitine palmitoyltransferase type-2 (CPT2) deficiency." (PMID 23326270, 2012). "Importantly, in vitro transcriptomic analysis has demonstrated that CPT2 is amongst the top 1% of genes whose mRNA levels are perturbed by 75 drugs (including statins) that can cause rhabdomyolysis." (PMID 31861911, 2019). "Patients deficient in CPT2 present with many of the same symptoms as patients deficient in VLCAD, including exercise-induced decompensation and rhabdomyolysis." (PMID 41100184, 2025). "Rare variants in several metabolic myopathy genes including CACNA1S, CPT2, LPIN1, PYGM and RYR1 increase myopathy/rhabdomyolysis risk following statin exposure." (PMID 31861911, 2019).
hepatocellular carcinoma (18 papers, 2019 to 2025). A malignant tumor that arises from hepatocytes. "Scientific findings emphasize that CPT2 is pro-cancer in hepatocellular carcinoma and is significantly correlated with tumor histological differentiation and venous infiltration." (PMID 39596847, 2024). "Studies have shown that orlistat treatment reduces the enzyme activity and expression of CPT2 and has a stronger therapeutic effect on growth inhibition and apoptosis in hepatocellular carcinoma after combination treatment with paclitaxel." (PMID 39596847, 2024). "It has been reported that, in patients with nonalcoholic steatohepatitis (NASH), lipotoxicity for hepatocellular carcinoma (HCC) cells is thwarted by CPT2 downregulation-mediated suppression of FAO." (PMID 38921447, 2024). "More recently, it has been demonstrated that the downregulation of CPT2 is highly significant in predicting hepatocellular carcinoma (HCC)." (PMID 38765144, 2024). "Silencing of CPT2 contributes to the metastatic and tumorigenic activity of hepatocellular carcinoma cells." (PMID 37251324, 2023). "Silencing CPT2 not only enhances the tumorigenic activity and metastatic potential, but also induces chemoresistance to cisplatin in hepatoma cells." (PMID 35646898, 2022). "CPT2 silencing is reported to facilitate the tumor progression of hepatocellular carcinoma, which is reconfirmed by our results." (PMID 36185199, 2022). "CPT2 down-regulation is important in enabling hepatocellular carcinoma (HCC) cells to escape lipotoxicity but also hepatocarcinogenesis is enhanced." (PMID 36195841, 2022). "Studies have shown that in hepatocellular carcinoma, CPT2 is the rate-limiting enzyme for fatty acid oxidation." (PMID 33029112, 2020). "CPT2 dysregulation may contribute to the development of MASLD and MASLD-associated hepatocellular carcinoma, which is why it has gained attention as a possible drug target." (PMID 41301863, 2025). "Numerous studies have shown that CPT2 is oncogenic in hepatocellular carcinoma, colorectal carcinoma, renal clear cell carcinoma, and primary ovarian plasmacytoid carcinoma, and is associated with proliferation, migration, invasion, stemness, apoptosis, and chemo-resistance of cancer cells." (PMID 39596847, 2024). "Compared with other colorectal, ovarian, and renal clear cell carcinomas, the mechanism of CPT2 in hepatocellular carcinoma has been relatively well studied, and the studies have placed more emphasis on upstream transcription factors, inhibitors of CPT2, and the effects of combinations of drugs." (PMID 39596847, 2024). "CPT2 plays a critical role in regulation of fatty acid oxidation and might promote carcinogenesis in liver cancer by leading hepatocellular carcinoma to lipid-rich environment." (PMID 31885736, 2019). "The same study found that E2F1 and E2F2 could also act as upstream transcriptional repressors of CPT2 in nonalcoholic steatohepatitis-induced hepatocellular carcinoma and that low expression of CPT2 could provide the lipid-rich environment required for hepatocarcinogenesis." (PMID 39596847, 2024). "Knockdown of CPT2 can promote adipogenesis in cancer cells through upregulation of stearoyl coenzyme A desaturase 1 (SCD1), which significantly enhances hepatocellular carcinoma tumorigenicity, metastatic potential, and cisplatin resistance." (PMID 39596847, 2024). "CPT2 is a key regulatory enzyme of FAO, which is closely related to the invasion, proliferation, migration, and chemical resistance to cisplatin of hepatoma cells." (PMID 36195841, 2022). "Carnitine palmitoyltransferase-2 (CPT2), a rate-limiting enzyme of FAO, was downregulated in cisplatin-resistant hepatocellular carcinoma." (PMID 33804114, 2021).
hepatocellular carcinoma (continued). "This was also demonstrated in animal experiments, where CPT2-Azo resulted in the most tumor-killing and inhibitory effects in hepatocellular carcinoma compared to other groups, and since CPT2-Azo was not converted to the more toxic CPT in normal cells, MCA produced little non-essential toxicity." (PMID 37630208, 2023).
breast carcinoma (17 papers, 2019 to 2026). "Enhanced CPT1A/CPT2 expression was detected in the recurrent human breast cancers and associated with a worse prognosis in breast cancer patients." (PMID 31803610, 2019). "CPT2 is highly expressed in recurrent breast cancer and associated with poor prognosis of patients." (PMID 37251324, 2023). "Similarly, it has been found that the increased expressions of CPT1 and CPT2 are associated with the resistance to radiotherapy of breast cancer." (PMID 34603046, 2021). "The mechanism by which CPT2 mediates radiotherapy resistance in breast cancer cells is analogous to that of CPT1." (PMID 39834807, 2024). "The HER1/2-MEK-ERK1/2-CPT1A/CPT2 axis reportedly enhances cell proliferation and confers radiation resistance in breast cancer." (PMID 39607749, 2024). "It is worth noting that enhanced expression of CPT2 was not only found in the recurrence of human breast cancer but was also found involved in the poor chances of breast cancer recovery." (PMID 36195841, 2022). "Following cytotoxicity assays using breast cancer MCF-7 cells revealed that CPT2 offered a similar cytotoxicity (62% reduced cell proliferation) to free CPT (68%), while toxicity of CPT1 was significantly lower (39%)." (PMID 33805680, 2021). "It was also reported that CPT1A and CPT2—known target genes of PPARα—are involved in the radiation resistance of breast cancer stem cells and overall survival of breast cancer." (PMID 33466690, 2021). "In the present study, we examined the protein expression of the three remaining components of the carnitine system (CACT, CPT2, and CrAT) and confirmed their expression and deregulation in canine mammary tumor tissues and cells." (PMID 34679988, 2021). "Immunoreactive CPT2 bands were detected in both normal and mammary tumor tissues with the expected molecular weight and varying signal intensity." (PMID 34679988, 2021). "Of note, CPT1A/CPT2 expression was also elevated in human recurrent breast cancer tissues compared to biopsy tumors." (PMID 31803610, 2019). "CPT2 increase promotes the growth and radiation resistance of breast cancer cells." (PMID 37251324, 2023). "Blocking FAO via FAO inhibitor or by CRISPR-mediated CPT1A/CPT2 gene deficiency inhibited radiation-induced ERK activation and aggressive growth and radioresistance of radioresistant breast cancer cells and radiation-derived breast cancer stem cells." (PMID 34217300, 2021). "Similarly, studies have shown that knockdown of CPT2 or the use of FAO inhibitors in recurrent breast cancer significantly inhibited ERK expression and cell stemness in radiotherapy-resistant cells, thereby improving the efficacy of radiotherapy in recurrent breast cancer cells." (PMID 39596847, 2024). "Thus, targeting CPT1A/CPT2 as well as other mitochondrial FAO elements may serve as a metabolic target to enhance the efficacy of breast cancer radiotherapy." (PMID 31803610, 2019). "Blocking FAO by CRISPR-mediated CPT1A/CPT2 KO inhibited aggressive phenotype of the radioresistant BC with down-regulation of the ERK pathway, indicating a potential metabolic target in breast cancer radiotherapy." (PMID 31803610, 2019). "L-carnitine, short-chain acylcarnitines, and three carnitine-mediated enzymes: carnitine palmitoyltransferase 1 A (CPT1A), carnitine palmitoyltransferase 2 (CPT2), and carnitine acetyltransferase (CRAT) were all up-regulated in breast cancer tissues." (PMID 37120513, 2023). "Blocking fatty acid oxidation by knocking out CPT1A/CPT2 via CRISPR-mediated has been shown to inhibit the invasive phenotype of radiotherapy-resistant breast cancer, suggesting that CPT2 is a potential metabolic target for breast cancer radiotherapy." (PMID 34740325, 2021). "CPT1A (Carnitine palmitoyl transferase I) and CPT2 (Carnitine palmitoyl transferase II) are two known target genes of PPARα, which increase fatty acid oxidation (FAO) required for the cell metabolism in radioresistant breast cancer cells and radiation‐derived breast CSCs." (PMID 36226253, 2022).
VLCAD deficiency (15 papers, 2014 to 2026). "Fibroblasts from patients with CPT2 or VLCAD deficiency typically exhibited markedly reduced palmitate oxidation capacities (from 1.3 to 3.3 nmol/h/mg), compared to control fibroblasts (5.2 ± 0.2 nmol/h/mg)." (PMID 24898617, 2014). "This trial was an open-label, non-randomized, and multicenter study of bezafibrate treatment in five patients with very long-chain acyl-CoA dehydrogenase (VLCAD) deficiency and one patient with carnitine palmitoyltransferase-II (CPT-2) deficiency (median age, 15.9 years; range, 5.8–26.4 years)." (PMID 31372341, 2019). "Altogether, these data suggest that trans-RSV, some of its metabolites, and other stilbenes might act in concert to stimulate FAO in human, and, remarkably, could improve mild CPT2 or VLCAD deficiency in patient fibroblasts." (PMID 30925787, 2019). "This trial was an open-label, non-randomized, and multicenter study of bezafibrate treatment in 6 patients with very long-chain acyl-CoA dehydrogenase (VLCAD) deficiency and 2 patients with carnitine palmitoyltransferase-II (CPT-2) deficiency (median age, 8.2 years; ranging from 5.8 to 26.4 years)." (PMID 29552494, 2018). "However, the majority of patients diagnosed with CPT2 or VLCAD deficiency presents the so-called “mild” phenotype, characterized by isolated myopathy of adolescence or adult-onset." (PMID 27136581, 2016). "On the other hand, the wide potential of this natural compound, its low price, and its excellent tolerance in humans, are strong incentives to further characterize its effects, especially for possible applications in diseases with few treatments to date, such as CPT2 or VLCAD deficiency." (PMID 24898617, 2014). "This led us to test the effects of RSV in ß-oxidation deficient fibroblasts, and these initial studies established that exposure to RSV (75 μM) could normalize FAO capacities in patients cells with the muscular form of CPT2 or VLCAD deficiency." (PMID 24898617, 2014). "This review covers CPT2 deficiency (CPT2D), CACT deficiency (CACTD), VLCAD deficiency (VLCADD), MTP deficiency (MTPD), and LCHAD deficiency (LCHADD)." (PMID 40983718, 2025). "As for most FAO disorders, there are to date no treatment for CPT2 or VLCAD deficiency." (PMID 27136581, 2016). "Of note, in a limited number of patients with the muscular form of CPT2 or VLCAD deficiency, the FAO defect is not expressed in the patient fibroblasts." (PMID 30925787, 2019).
cardiomyopathy (11 papers, 2014 to 2025). A disease of the heart muscle or myocardium proper. "Cardiomyopathy is a common symptom associated with the severe infantile hepatocardiomuscular form of CPT2 deficiency." (PMID 39199302, 2024). "Since deficiencies of either ACADVL or CPT2 can cause cardiomyopathy and arrhythmias in newborns and early infancy, the substantial reduction of FA uptake and oxidation in BTHS hearts likely contributes to the cardiomyopathy phenotype." (PMID 37930434, 2023). "CPT-2 deficiency (AR) is categorized into 3 forms: a myopathic form, a severe infantile form (recurrent hypoglycemia, liver dysfunction, rhabdomyolysis and cardiomyopathy) and a lethal neonatal form." (PMID 41425985, 2025). "In contrast, cardiomyopathy and heart rhythm disorders have been described in CACT deficiency and in CPT2 deficiency." (PMID 41425985, 2025). "In patients with severe genetic defects of Cpt2, cardiomyopathy is common, and medium-chain fatty acid-enriched diet is used as therapy." (PMID 33757734, 2021). "Furthermore, similar enzymatic activities of carnitine palmitoyltransferase I and 2 (CPT-1 and CPT-2) were observed in LV tissue homogenates from male patients with BTHS-related cardiomyopathy compared to non-failing controls." (PMID 36035919, 2022).
Obesity (11 papers, 2017 to 2025). Accumulation of substantial excess body fat. "It upregulates fatty acid oxidation genes like Pparα, Acsl, Cpt1, and Cpt2, thereby inhibiting liver inflammation and lipid synthesis while promoting fatty acid oxidation to address obesity induced by a high-fat diet in mice." (PMID 39459158, 2024). "In our previous study, we also showed that the downregulation of CPT2 in obesity- and NASH-driven HCC was, at least in part, attributed to decreased peroxisome proliferator-activated receptor alpha (PPARα)." (PMID 30445800, 2018). "We further analyzed the significance of CPT2 downregulation in obesity-mediated hepatocarcinogenesis." (PMID 30445800, 2018). "Importantly, the expression of CPT2 was also downregulated in human SH-HCC, and NASH patients with HCC showed increased serum levels of acylcarnitine, suggesting that a similar metabolic change may occur in human obesity-mediated HCC." (PMID 30445800, 2018).